IGFBP7 (insulin like growth factor binding protein 7)
Diseases named in the same sentence as IGFBP7 in open-access papers (continued):
Sharing a sentence is not in itself a finding about the gene and the disease.
tumor (continued). "In marked contrast to these reports, the low expression of IGFBP7 was also found to be associated with tumor progression and patients' poor survival in carcinoma of the stomach." (PMID 32500027, 2020). "For LUSC1, all the single tumor cells had the clonal mutation (R45P) in Igfbp7 and a subset of single tumor cells had the mutation (R2457S) in Igf2r." (PMID 29484121, 2018). "Expression of IGFBP-7 in tumour-associated fibroblasts can also promote colony formation when epithelial tumour cells are cocultured with IGFBP-7-expressing cancer-associated fibroblasts (CAFs) by secondary paracrine tumour-stroma interactions." (PMID 25866791, 2015). "This is the first evidence of the mechanism underlying the high IGFBP7 expression in fibroblasts during tumor-stroma interactions." (PMID 24427302, 2014). "In contrast to IGFBP7, αvβ3 integrin expression is also associated with non-tumour angiogenic vessels and tumour cells." (PMID 20959824, 2010). "It is also reported that IGFBP7 suppression is associated with rapid tumour growth and tumour invasiveness." (PMID 20407444, 2010). "We showed that CD93 mainly played roles in the tumor-associated vasculature, MMRN2 mainly played roles in the quiescent vasculature, and IGFBP7 could play roles in both the quiescent and tumor-associated tumors vasculature." (PMID 37660019, 2023). "The tumor mutation burden was significantly higher in the IGFBP7 low group." (PMID 35812369, 2022). "Likewise, tumor mutation burden was calculated and compared between the high- and low-IGFBP7 groups." (PMID 35812369, 2022). "We found that IGFBP7 was negatively associated with T cells recognition and tumor cell killing." (PMID 35812369, 2022). "In addition, we also analyzed the correlations between IGFBP7 expression and immune markers of tumor associated macrophages (TAMs), M1 macrophages, dendritic cells, T cells and neutrophils." (PMID 33531979, 2021). "On the other hand, ascorbate treatment was also associated with increase in IGFBP7, a known tumour suppressor that is thought to compete with insulin-like growth factor binding or cause oncogene-induced senescence, and has been recently shown to be produced by macrophages." (PMID 33799728, 2021). "We hypothesize that host factors impact tumor-specific IGFBP7 levels and that IGFBP7 is associated with tumor characteristics." (PMID 34606580, 2021). "Since the tumor’s malignancy is highly correlated with the degree of angiogenesis, the use of anti-IGFBP7 sdAb linked to a contrast agent for tumor vascular imaging could aid in the diagnosis and clinical management of brain tumors." (PMID 31544833, 2019). "Previous analyses have demonstrated that the molecular mechanism in tumor cells underlying vincristine resistance is complex and involves a number of genes, including insulin-like growth factor binding protein 7 and multidrug resistance protein 1, in addition to long noncoding RNA." (PMID 31010006, 2019). "Notably, IGFBP7, which also underwent evolutionary acceleration as detected by phyloP, may be associated with multiple gene functions, including body growth and tumor suppression." (PMID 37872505, 2023). "Also, we investigate whether IGFBP7 messenger ribonucleic acid (mRNA) expression is associated with the patient and tumor characteristics and other proteins in the IGF/insulin-signaling pathway." (PMID 34606580, 2021). "Interestingly, Mdk and Igfbp7, the tumor-intrinsic factors associated with resistance to tipifarnib, were also upregulated in MyoCAFs in the tipifarnib-treated group, implying key roles for these two targets in dormant tumor cells." (PMID 32460812, 2020). "Thus, our results, suggest that underexpression is associated with tumourigenicity and that expression of IGFBP7 may be important for tumour suppressor pathway phenotype." (PMID 25886299, 2015).
tumor (continued). "Thus, in accordance with several reports suggesting that IGFBP-7 acts as a tumor suppressor, loss of IGFBP-7 may provide tumor cells with a growth advantage under conditions of local nutrient deprivation, such as in prevascularized stages of tumorigenesis." (PMID 18412985, 2008). "IGFBP7 suppresses tumor cell proliferation and migration by inhibiting the expression of EGR1, thereby downregulating the activity of the TGF-β1 signaling pathway." (PMID 41692778, 2026). "Previous studies have demonstrated that IGFBP7 is significantly associated with poor prognosis in GBM and promotes tumor angiogenesis, thereby contributing to drug resistance." (PMID 41020875, 2025). "Tumor-derived TGF-β1 induces IGFBP-7 in myofibroblasts, which positively regulates tumor proliferation and metastasis and can be attenuated by TGF-β receptor antagonists." (PMID 41226289, 2025). "Our thorough investigation concludes by demonstrating the crucial function of IGFBP7 in controlling the immunological milieu surrounding tumours and lactic acid metabolism, eventually leading to immunotherapy resistance in STAD." (PMID 39788916, 2025). "While the exact mechanisms by which IGFBP7 influences tumour progression and treatment response are complex and context‐dependent, emerging evidence suggests that it plays a multifaceted role in cancer development, progression and immunotherapy." (PMID 39788916, 2025). "Functioning as an extracellular matrix protein, IGFBP7 regulates fundamental biological processes such as proliferation, apoptosis, and migration, and significantly influences tumor development and angiogenesis." (PMID 40943530, 2025). "Elevating IGFBP7 level promotes tumor progression by enhancing TAM/M2 macrophage polarization through the FGF2/FGFR1/PI3K/AKT axis in GC59,60." (PMID 40032943, 2025). "In vitro analysis using an esophageal carcinoma cell line indicated that increasing IGFBP-7 using an adenovirus system can directly induce SMAD2/3 activation and promote expression of TGF-β1, positively associated with tumor development." (PMID 41226289, 2025). "Knockdown of DUSP6 increases levels of insulin growth factor binding protein 7 (IGFBP7), a secreted protein regarded as a tumor suppressor, indicating that DUSP6 regulates IGFBP7." (PMID 41210685, 2025). "IF staining of subcutaneous tumor sections was performed to confirm the regulatory effects of IGFBP7 on ZO‐1 in vivo." (PMID 39698844, 2025). "In conclusion, this work sheds light on the mechanisms by which the lactate metabolism‐related indicator IGFBP7 affects the tumour immune milieu and the response to immunotherapy in STAD." (PMID 39788916, 2025). "IGFBP7 exhibits a dual role in cancer, exerting antitumor effects by inhibiting tumor cell growth and accelerating apoptosis, while also inducing a disordered tumor vasculature system by binding to CD93." (PMID 40943530, 2025). "Here, we report the mechanistic insights into how IGFBP7 modulates the tumour immune microenvironment and present its potential as a predictive biomarker and therapeutic target for STAD immunotherapy." (PMID 39788916, 2025). "Overexpression of IGFBP-7 accelerates tumor proliferation and invasion in vitro, whereas a knockdown reduces proliferation and metastatic potential." (PMID 41226289, 2025). "IGFBP7 has been found to promote the proliferation and migration of vascular endothelial cells in tumor vasculature and, therefore, is expected to be a potential target for tumor therapy." (PMID 38840498, 2024). "This is consistent with previous studies showing that both systemic and tumor-specific IGFBP7 protein levels were poor prognostic markers in breast cancer, and are also in line with our results from SCAN-B." (PMID 39362991, 2024). "A xenograft animal model was used to further investigate the effects of IGFBP7 on tumour growth in vivo." (PMID 39351597, 2024).
tumor (continued). "This justifies laboratory studies to address gaps in knowledge concerning the roles of IGFBP7 in neoplasia, and the relevance of this protein to IGF-1R-targeting agents." (PMID 39362991, 2024). "It affects the tumour microenvironment and T cell activity, with an IGFBP7‐based model effectively predicting prognosis and treatment response." (PMID 39400959, 2024). "The highest tumor-to-control ratio (fold change) was found in T1 and T2 carcinomas for both IGFBP7 and ANXA1 in the array analysis." (PMID 38893148, 2024). "When considering the STAD grade, IGFBP7 expression was greater in Grade 3 tumours than Grade 2 tumours." (PMID 39351597, 2024). "The results suggested that IGFBP7 knockdown (shIGFBP7) significantly attenuated tumour growth compared with that in the control group." (PMID 39351597, 2024). "IGFBP7, known to play various roles in multiple tumours, is complexly regulated across diverse cancer types, as evidenced by our pancancer analysis." (PMID 39351597, 2024). "Blockade of the CD93/IGFBP7 interaction by monoclonal antibodies thus promoted vascular maturation and reduced leakage, leading to reduced tumor hypoxia and increased tumor perfusion." (PMID 39045455, 2024). "To evaluate the biological role of IGFBP7 in GC, we conducted a correlation analysis of the expression of oncogenes and tumour metastasis‐related genes (MRGs)." (PMID 39351597, 2024). "Paired Student's t‐test also suggested that IGFBP7 was significantly upregulated in STAD tumour tissues compared with paired normal tissues." (PMID 39351597, 2024). "Within the tumorigenesis context, IGFBP7 was suggested to function as a “double-edged sword” in cancer progression, acting as an oncogene in some and as a tumor-suppressor in other cancer types." (PMID 39045455, 2024). "With respect to tumour invasion depth, IGFBP7 expression was significantly elevated in tumours with advanced invasion depth." (PMID 39351597, 2024). "CAF expressing IGFBP7 induce colony formation when co-culturing with CRC cells through paracrine tumor–stromal interaction." (PMID 38478111, 2024). "IGFBP7 expressed by tumor endothelial cells suppresses IGF1R signaling and the stem-cell-like property of tumor cells." (PMID 38576482, 2024). "When samples were grouped based on tumour stage, IGFBP7 was upregulated in stage II/III/IV tumours compared with stage I tumours." (PMID 39351597, 2024). "Analysis of The Cancer Genome Atlas and endothelial specific online database (EndoDB) demonstrate that IGFBP7, a secreted ECM protein implicated in a variety of homeostatic processes, is upregulated on tumor endothelium." (PMID 38468017, 2024). "In STAD, IGFBP7 was upregulated in tumour tissues compared with normal tissues when only the TCGA database was used or when the TCGA and GTEx databases were combined." (PMID 39351597, 2024). "In this review, we focus on the roles of IGFBP7 in tumor development, acute kidney injury, and reproduction due to their significant impact on clinical outcomes and the extensive research supporting IGFBP7’s involvement in these areas." (PMID 39081862, 2024). "For example, several research teams have reported that IGFBP7 is highly expressed in tumor cells, thereby promoting tumor angiogenesis, and that blockade of IGFBP7 significantly impairs tumor vascular remodeling." (PMID 38840498, 2024). "Overall, IGFBP7 exhibits a dual role in tumor development, inhibiting tumor cell growth and accelerating tumor cell apoptosis, thus emerging as a potential candidate for tumor suppression." (PMID 39081862, 2024). "Despite some conflicting conclusions, the majority of evidence currently suggests that IGFBP7 inhibits tumor cell growth and promotes tumor cell apoptosis, rendering it a potential candidate for tumor suppression." (PMID 39081862, 2024).
tumor (continued). "We found that CAF subtypes 0 (BTG1+ CAF), 2 (CFD+ CAF), and 4 (IGFBP7+ CAF) were more abundant in the tumor than the normal, while CAF subcluster 1 (OGN+ CAF), 3 (C1R+ CAF), 5 (MFAP5+ CAF), and 6 (SFRP4+ CAF) were more abundant in the normal than the tumor." (PMID 38686196, 2024). "In total n = 8 LSCC and n = 6 control tissue lysate samples (malignancy-free tumor-distant tissue) were analyzed for IGFBP7 and ANXA1." (PMID 38893148, 2024). "The ELISA results of our study showed a 1.7-fold increase in IGFBP7 serum levels in comparison to the control group for all tumor stages." (PMID 38893148, 2024). "IGFBP7 also promotes tumor vascularization and formation, favoring tumor metastasis, while anti-IGFBP7 inhibits tumor vascularization and angiogenesis." (PMID 38840498, 2024). "IGFBP7 primarily exerts its anti-tumor effects by inhibiting tumor cell growth and accelerating tumor cell apoptosis." (PMID 39081862, 2024). "Vascular invasion within the tumor and high expression of CUB domain-containing protein (CDCP1) and low levels of insulin-like growth factor binding protein (IGFBP5 and IGFBP7) in the bloodstream have been reported as risk factors for lymph node recurrence." (PMID 38472943, 2024). "Insulin-like growth factor-binding protein 7 (IGFBP7) has been identified as a potential tumor suppressor in HCC, and the secretion of IGFBP7 was significantly decreased in senescent HSCs in favor of tumor growth and progression." (PMID 37649614, 2023). "In the tumor vasculature, hypoxia, VEGF, and TGF-β1 were associated with IGFBP7 expression in vascular ECs." (PMID 37660019, 2023). "By methylation-specific PCR, they proved that IGFBP7 methylation is more prevalent in tumour tissue than in adjacent normal tissues (90% vs. 59%)." (PMID 37660019, 2023). "IGFBP7 expression was upregulated during physiological and pathological angiogenesis processes, such as brain injury and tumor neovascularization." (PMID 37660019, 2023). "The IGFBP7 protein was mainly located in the stromal region, where it is attached to and acts around the tumor cells, consistent with our single-cell data analysis results." (PMID 37568781, 2023). "Recent advances have shown that IGFBP7 appears to exhibit IGF-independent biological effects in tumor progression." (PMID 36681667, 2023). "They reported that the IGFBP7 expression level is upregulated in GC and is related to tumour stage, tumour grade, tumour status, and Helicobacter pylori infection." (PMID 37660019, 2023). "Igfbp7 knockout mice displayed a proinflammatory status, with a high incidence of tumor development upon carcinogen treatment." (PMID 37394588, 2023). "Specifically, IGFBP7 secreted by CAFs can bind to receptors on the surface of tumor cells, leading to the activation of downstream oncogenic signaling pathways." (PMID 37568781, 2023). "Next, we determined the relationships of IGFBP7 with age of diagnosis, gender, IDH mutation and tumor grade." (PMID 36043552, 2023). "The role of IGFBP7 in tumor progression is complicated, since IGFBP7 exhibits opposite roles in different cancers." (PMID 36681667, 2023). "IGFBP7 is notably elevated in undifferentiated tumors, indicating its potential role in tumor differentiation." (PMID 37568781, 2023). "As a member of the IGFBP family with relatively low affinity to IGF-1 and IGF-II, IGFBP7 appears to play roles in tumor progression in an IGF-independent manner." (PMID 36681667, 2023). "IGFBP7 can regulate the mechanism of antigen presentation, thereby generating a response of anti-tumor immune." (PMID 37088808, 2023). "In fact, the authors showed that IGFBP7 and CD93 expression was significantly increased in tumor-associated endothelial cells." (PMID 37443812, 2023). "It is possible that IGFBP7 in CRC has functionally opposite roles in the stromal versus epithelial compartment of the tumour, explaining its prognostic significance specifically in the stroma in the present study." (PMID 34874125, 2022).
tumor (continued). "Compared to virus-specific Th1 cells, this tumor-specific CD4+ T cell state differentially expressed genes associated with Th2 cells, including Igfbp7, Ccl1, Ccr8, and Il13, and downregulated Th1-associated genes, including Ccl5 and Ly6c2." (PMID 35829695, 2022). "Endothelial cells treated with NMU also change their phenotype, increase the production of IGFBP-7 and vimentin, markers of tumour endothelial cells (TECs), and become more motile with an increased ability to form capillaries." (PMID 36482448, 2022). "The role of IGFBP7 in BLCA is still unclear, and more evidence is needed to explore the association between IGFBP7 and tumor immunologic features." (PMID 35812369, 2022). "In some tumors, IGFBP7 exhibits tumor suppressor activity in certain cancer types via regulation of cell proliferation, apoptosis, cell adhesion epithelial mesenchymal transition (EMT) and angiogenesis." (PMID 35812369, 2022). "More recently, IGFBP7 knockdown in a CRC cell line was found to induce an EMT phenotype, and IGFBP7 overexpression resulted in significantly smaller tumours with fewer lung metastases in a murine model." (PMID 34874125, 2022). "IGFBP7 was originally identified in normal mammary epithelial cells and meningeal cells, and its expression pattern varies with tumor type." (PMID 35812369, 2022). "In the tumor immunity cycle, IGFBP7 enhanced the release of cancer cell antigens, trafficking of immune cells to tumors and infiltration of immune cells into tumors." (PMID 35812369, 2022). "The reported pleiotropic roles of IGFBP-7 suggest a potential switch in biological properties with tumor progression, similar to that of TGF-β." (PMID 33767994, 2021). "The results revealed that the mRNA expression of IGFBP7 was significantly increased in the G3 phase (P<0.001), advanced tumor status (T2/3/4) (P<0.001) and advanced stages (II/III/IV) (P<0.05)." (PMID 33531979, 2021). "Overexpression of IGFBP7 suppressed cell growth, tube formation, tumor development, and neovascularization in a chicken embryo." (PMID 33669204, 2021). "The genes listed as involved in androgen-independent pathway, such as MAPK12, and IGFBP7, all exhibited higher expressions in LNCaP xenograft tumor as compared to cultured cells." (PMID 33808801, 2021). "More knowledge is needed concerning the interplay between IGFBP7, patient and tumor characteristics and prognosis." (PMID 34606580, 2021). "Given the reported biological significance of interactions between IGF-I, IGFBP-7, and IGF-IR, correlations between preoperative circulating IGF-I, IGFBP-3, and IGFBP-7 levels, and tumor IGF-IR membrane (IGF-IRm) expression were assessed." (PMID 33767994, 2021). "Tumor-specific IGFBP7 protein levels were evaluated with immunohistochemistry using tissue microarrays in tumors from 878 patients." (PMID 34606580, 2021). "Using large transcriptome sequencing data, we demonstrated that IGFBP7 mRNA was overexpressed in GC specimens and correlated with stage, grade, tumor status and H. pylori infection." (PMID 33531979, 2021). "The current findings reveal that the mRNA expression of IGFBP7 is divergent in different cancers, which suggests that IGFBP7 functions as both an oncogene or tumor suppressor according to the cancer types." (PMID 33531979, 2021). "In colon cancers, TGFβ activation is induced in CAFs, which can contribute to the upregulation of IGFBP7, a TGFβ-induced gene product secreted by tumor cells." (PMID 33669204, 2021). "The IGFBP7 secreted by tumor cells can promote anchorage-independent growth and colony formation in malignant mesenchymal cells and in epithelial cells with an EMT phenotype." (PMID 33669204, 2021). "Tumor-specific IGFBP7 protein levels were categorized based on Histo 300 scores into IGFBP7low (6.2%), IGFBP7intermediate (75.7%) and IGFBP7high (18.1%)." (PMID 34606580, 2021).